FAM236B (family with sequence similarity 236 member B)
Gene: Protein-coding gene on chromosome X (72,781,865 to 72,782,660, reverse strand). Ensembl gene ENSG00000268994.
Homologues: Orthologues: mouse Fam236e (34% identical), rat Fam236d (34% identical), mouse Fam236f (33% identical). Paralogues in human: FAM236A (100% identical), FAM236C (91% identical), FAM236D (91% identical).